IL10 (interleukin 10)
Diseases named in the same sentence as IL10 in open-access papers (continued):
Sharing a sentence is not in itself a finding about the gene and the disease.
colitis (continued). "IL-10 promotes the proliferation and differentiation of B cells into IgA-secreting plasma cells and also acts as an anti-inflammatory cytokine to inhibit NKT cell-mediated colitis and protect intestinal mucosa by regulating the expression of CD1d in intestinal epithelial cells." (PMID 36425118, 2022). "The decreased expression of proinflammatory cytokine and increased expression of anti-inflammatory cytokine were also observed in the miR-200b-3p- and miR-181b-5p-treated colitis groups, including IL-6, IL-1β and IL-10, but no significant changes in IL-22 was observed." (PMID 36176029, 2022). "The results showed that ERE treatment alleviated DSS-induced colitis, which was characterized by decreases in disease activity index (DAI) scores, spleen index and colon levels of TNF-α and IL-6, mitigation in pathological damage and oxidative stress and increases in colon length and IL-10 levels." (PMID 36295859, 2022). "Therefore, we suggest that the absence of CCR2 interferes with the development of colitis in mice lacking the receptor for IL10 without altering the expression of its ligand CCL2." (PMID 35013585, 2022). "In contrast, SAA1 expression was inhibited by IL-10, but this result was not statistically significant, which is consistent with previous reports demonstrating that IL-10 is an anti-inflammatory cytokine that can suppress colitis." (PMID 35303008, 2022). "Taken together, these findings indicate that impaired regulatory mechanisms mediated by CD103+ DC, Treg, or Bregs are preserved in IL-10−/−/β7−/− mice and do not appear to play a major role on the aggravation of colitis, under the specific conditions of our IL-10−/− mouse colony." (PMID 34433904, 2022). "(100, 300 mg/kg) could improve the syndrome of TNBS-induced colitis mice by regulating the MPO and MDA contents and the levels of pro-inflammatory (TNF-α, IL-6, L-1β, IL-12, IFN-γ, IL-2, IL-17) cytokines and anti-inflammatory cytokines (IL-4, IL-10)." (PMID 36160392, 2022). "We found CA could enhance anti-inflammatory cytokine IL-10 level to inhibit inflammatory response, which indicates that CA treatment not only inhibits inflammatory response but also enhances anti-inflammatory capacity in DSS-induced colitis mice." (PMID 34867926, 2021). "We found that Il33 is significantly increased in DSS-induced colitis, but not in Il10−/− colitis." (PMID 33953267, 2021). "This secondary regulatory response is absent in IL-10–/– mice, which may lead to intestinal inflammation directly and may eventually drive toward colitis." (PMID 34603258, 2021). "Mice lacking IL-10 (IL-10−/− mice) spontaneously develop a Th1-driven colitis." (PMID 34944544, 2021). "Interestingly, the ability of H. hepaticus to trigger IBD in IL-10−/− mice depends on the presence of an indigenous microbiota, as ex-germfree mice mono-colonized with H. hepaticus do not develop severe colitis." (PMID 34126769, 2021). "Interestingly, gut microbiota seemed to play a crucial role in the development of colitis in this mouse model, as germ-free IL-10−/− mice did not develop colitis and the administration of antibiotics prevented colitis." (PMID 33435303, 2021). "Interestingly, IL-33 is strongly induced during DSS-induced colitis, but not during IL-10–/– chronic colitis." (PMID 33953267, 2021). "However, oral gavage of NK210 or NK219 suppressed LPS-induced colitis: they decreased myeloperoxidase activity, NF-κB+/CD11c+ cell population, and IFN-γ to IL-10 and TNF-α to IL-10 expression ratios in the colon while colon shortening was not significantly increased." (PMID 34667205, 2021). "Further, the percentage of Foxp3+ IL-10+ TGF-β+ natural Tregs, Foxp3− IL-10+ TGF-β− induced Tregs, CD127− induced Tregs and CD8+ Tregs was measured at different time points in DSS-induced experimental colitis model in murine lamina propria lymphocytes, mesenteric lymph nodes and peripheral blood." (PMID 34440615, 2021).
colitis (continued). "For example, lack of IL-22 in the IL-10–/– mice model prevents spontaneous colitis development." (PMID 34603258, 2021). "Notably, mutant zebrafish lacking functional IL-10 did not develop spontaneous colitis, but did express increased levels of interferon (IFN)-γ in the gills." (PMID 34603258, 2021). "Although it is difficult to delineate which route is more important for suppressing ER stress (IL-10 vs γ-glutamylcysteine) in our model, we speculate that both work together during TNBS colitis to suppress inflammation and preserve goblet cell numbers and epithelial barrier integrity." (PMID 33985416, 2021). "However, the number of total Tregs was not increased in the colon of mice with colitis treated with rTsPmy even though the levels of IL-10 and TGF-β were significantly higher in the inflamed colon." (PMID 34336843, 2021). "Absence of CX3CR1 expression by colonic macrophages results in reduced secretion of IL-10 and failure in supporting lamina propria Treg cell expansion: accordingly, lack of CX3CL1-CX3CR1 signaling leads to a more sever dextran sulfate sodium (DSS)-induced colitis." (PMID 32650452, 2020). "The IL-10 cytokine family has been shown to facilitate the gut antimicrobial defense and promote mucosal barrier integrity and repair by activating STAT3, while IL-17, TNF-α, and IFN-γ induce colitis by disrupting the mucosal barrier function of the immune system." (PMID 32670220, 2020). "GF IL-10−/− mice lacked histologic evidence of colitis or other indicators of immune activation." (PMID 32133003, 2020). "Moreover, in vivo studies indicated that the CS-IGF-1C hydrogel promoted hP-MSC survival as visualized by BLI and markedly alleviated mouse colitis, which was possibly mediated by hP-MSC production of PGE2 and interleukin-10 (IL-10) production by polarized M2 macrophages." (PMID 32685014, 2020). "In parallel, we explored whether cotransplanted CS-IGF-1C hydrogel with hP-MSCs ameliorated colitis by promoting the release of PGE2 to promote the polarization of M2 macrophages, accompanied by the production of IL-10, reducing the level of M1 macrophages and proinflammatory cytokines." (PMID 32685014, 2020). "Colonization of GF IL-10−/− mice with either a murine fecal E. coli isolate, NC101, that was subsequently shown to have adherent-invasive characteristics, or the human oral isolate Enterococcus faecalis OG1RF led to colitis by histologic, clinic and immunologic measures." (PMID 32133003, 2020). "By contrast, lack of IL-10 signaling induces a proinflammatory profile on colonic MFs highlighted by IL-23 and IL-1β production, leading to recruitment of Th17 cells and promoting colitis." (PMID 33681185, 2020). "Lack of macrophage response to IL-10 results in the expression of several pro-inflammatory mediators and the development of colitis in mice: in particular, IL-23 secretion by IL-10Rα-negative macrophages induces IL-22 release by ILC3 and Th17 T cells, leading to the occurrence of colitis." (PMID 32650452, 2020). "Furthermore, achaete-scute complex homologue 2 (Ascl2) inhibits Th17 cell differentiation and restrains their pathogenicity via promoting Blimp-1-dependent IL-10 production, whereas Ascl2 was shown to be significantly downregulated in human IBD and experimental colitis." (PMID 32403220, 2020). "IL-10, IL-10Rα and IL-10Rβ mutant mice did not develop spontaneous colitis in our mouse facility." (PMID 30640950, 2019). "In TNBS-induced colitis, cytokine imbalance was demonstrated by high expression of proinflammatory cytokines (TNF-α, IFN-γ, IL-1β, and IL-17) and low expression of anti-inflammatory cytokines (IL-4 and IL-10) to induce inflammatory damage to the colonic mucosa." (PMID 30894816, 2019). "Although the control (PBS-treated) IL-10 KO mice used here did not develop severe colitis, they did display short colons, and low but detectable level of colon MPO activity, both suggestive of chronic inflammation, which was attenuated by flagellin immunization." (PMID 31827095, 2019).
colitis (continued). "However, mice lacking IL10RA27 in Treg that show reduced expression of IL-10, develop a more severe colitis, suggesting that compensatory mechanisms orchestrated by non-Treg can participate to maintain homeostasis through regulation of Treg function." (PMID 30992496, 2019). "Also, serum levels of both the proinflammatory cytokine TNF-α and anti-inflammatory IL-10 were higher (1.3-fold, P = 0.05) in ceftriaxone-pretreated rats vs. colitis group without antibiotic treatment." (PMID 31437166, 2019). "However, the intestinal microbiota was shown to be essential for disease development, as GF Il10−/− mice do not develop colitis." (PMID 31396223, 2019). "Furthermore, IL-10 induced by cystatins is reportedly effective against dextran sodium sulfate (DSS)-induced intestinal inflammation, mucosal inflammation, and colitis." (PMID 31013806, 2019). "Furthermore, Il10−/− mice infected with H. hepaticus developed more severe colitis than uninfected mice at one institution but not at another; GF mice never developed colitis." (PMID 31703321, 2019). "The data showed that the induction of colitis using TNBS induced an increase in the expression of pro-inflammatory genes such as Tnf-α, Inf-γ, Il-1β, and Il-6 and, on the other hand, a reduction in the expression of anti-inflammatory cytokines such as Il-10 and Tgf-β." (PMID 30717413, 2019). "Strikingly, FOXP3+ specific conditional knock out mice for MAF did not develop colitis and demonstrated normal levels of IL-10 in their colon, despite the incapacity of regulatory T cells lacking MAF to suppress colon inflammation in Rag1−/− mice transferred with naïve CD4+ T cells." (PMID 30992496, 2019). "The expression of the anti-inflammatory cytokine IL-10 was similar between the two groups, suggesting that Fam96a's protective role in colitis may not be IL-10 dependent." (PMID 31803631, 2019). "In DSS colitis, we and others have shown that resident Mφs do not acquire proinflammatory characteristics, but this has been reported in models of colitis where IL-10-mediated signaling is absent, with wider alterations in gene expression than we tested here." (PMID 29203542, 2018). "In addition, the protective effect of Zn failed to overcome the exacerbated colitis observed in mice that did not respond to endogenous IL-10." (PMID 29545807, 2018). "The reduced IL-10+ T-cells and increased IFN-γ+IL-17+ T-cells in the LP of mice transferred with Gpr43−/− Th1 cells indicate that the SCFA-GPR43 interaction regulates Th1 cell function, thus providing a potential mechanism whereby Gpr43−/− Th1 cells induce more severe colitis." (PMID 30177845, 2018). "Furthermore, our results suggest that neither lymphocytes nor IL-10 are involved in the protective effect by FhEVs in DSS-induced colitis mice model." (PMID 29875750, 2018). "Hence, chronic IL-10−/− colitis facilitates intestinal infection with MDR Psae that does not lead to changes in gut microbiota composition." (PMID 29704005, 2018). "As such, the inhibition of IL-10-induced epithelial restitution could have also contributed to the more severe colitis demonstrated in mice lacking intestinal epithelial expression of the IL-10 receptor 1 in this study." (PMID 29922293, 2018). "We also generated IL-10-/- Erbin+/- mice (IL-10-/-Erbin-/- could not be available in our study) to determine the role of Erbin in colitis." (PMID 29552291, 2018). "In colitis, Breg-mediated suppression required IL-10 and not iNKT cells, as B cells could still suppress in the absence of iNKT cells." (PMID 29449556, 2018). "Increased IL-10 levels may be a compensatory response of the colon to dampen overly active inflammation, consistent with previous reports demonstrating higher IL-10 levels in more severely damaged colons using the same DSS-induced colitis model." (PMID 30455703, 2018). "Thus, the protective effects of IL-10 were not sustained over time, implying that IL-10 presence at the time of insult is necessary to prevent colitis." (PMID 29545807, 2018).
colitis (continued). "Thus, the DSS-induced colitis resulted in an increase in MPO, INF-γ, IL6, IL1-β, TNF-α, and IL10." (PMID 28528363, 2018). "In contrast, strains inducing a low IL-10/IL-12 cytokine ratio on human PBMC’s could not significantly attenuate colitis symptoms in mice." (PMID 28233848, 2017). "Whereas the current biomarkers, CRP and Lcn-2, did not discriminate between the DSS-induced and IL10−/− mouse models of colitis, our signature could make this distinction." (PMID 28566745, 2017). "Whether or not the reduced IL-10 production by Bcl-3-overexpressing Tregs is the sole reason for the colitis is not clear, as we also noticed decreased expression levels of Foxp3, CTLA-4, GITR and IL-2R in these Treg cells." (PMID 28452361, 2017). "Strains inducing higher levels of the anti-inflammatory cytokine IL-10 and lower levels of the pro-Th1 cytokines IL-12 and IFNγ after in vitro stimulation of human peripheral mononuclear cells (PBMC), offered the best protection in the in vivo colitis model used." (PMID 28233848, 2017). "Interestingly, after SPX, the treatment with α7 agonist lost completely its protective effects against colitis, being unable to lower IL-1β concentrations and exacerbating TNBS-induced increase of IL-6 levels, while leaving unmodified IFNγ and IL-10 colonic content with respect to SPX/C mice." (PMID 29167641, 2017). "As noticed above we observed particularly in DNBS-induced colitis an increase of IL-5, IL-17 and IFNγ in colon tissue of mice treated with LL-pILEMPTY compared to control group and a tendency to decrease IL10 even if the difference is not statistically significant." (PMID 28203226, 2017). "Interestingly, the macrophage migration inhibitory factor (MIF) homolog from Anisakis simplex (As-MIF) has also been shown to induce upregulation of IL-10 in both lymph node and intestinal epithelial cells, and also increases Foxp3+ Treg expression in mice subject to DSS-induced colitis." (PMID 28302598, 2017). "A closer look on other colitis models showed that the signature can also be used to distinguish across the various models: between TLR5−/− (green) and DSS D7 (orange) mice, between IL10−/− D98 mice (after colitis, red) and TLR5−/− mice (green) and between DSS D7 (orange) and IL10−/− D98 mice." (PMID 28566745, 2017). "We stained colon biopsies from E. faecalis-colonized Il10-/- mice for these factors and noted increased expression in colon epithelial cells for each compared to biopsies from sham-colonized mice that otherwise showed no colitis or cancer." (PMID 29254234, 2017). "The cure of murine colitis depends upon the production of IL-10; notably, our results demonstrated that treatment with 10 μg/kg H-SN1 could maintain a significantly higher mRNA expression level of IL-10 in the inflamed colon than in the control." (PMID 27158082, 2016). "Moreover, following wild type CD4+ T-cell transfer, Rag2−/− mice lacking both IL-10 and IL-22 signaling develop severe colitis, which cannot be rescued by exogenous IL-10." (PMID 27027442, 2016). "Importantly, the concentration of IL-10 was significantly higher (P < 0.05; Student's t-test) in sera of MSCs + Davanat-treated mice when compared to concentration of this cytokine in MSCs-only-treated mice with DSS-induced colitis." (PMID 27057168, 2016). "In conclusion, Davanat-induced inhibition of Gal-3 did not significantly affect potential of MSCs to attenuate colitis but managed to enhance production of anti-inflammatory cytokine IL-10 in colonic macrophages and to promote their polarization towards immunosuppressive M2 phenotype." (PMID 27057168, 2016). "Moreover, in vitro-generated Th17 cells expressing the CD39 ectonucleotidase produce IL-10 and are less pathogenic than CD39 negative Th17 cells in a model of experimental colitis in Rag-/- mice." (PMID 27322617, 2016).
colitis (continued). "Interestingly, we found that A. parvulum triggers the development of colitis in Il10−/− mice under specific pathogen-free conditions but not under mono-association conditions." (PMID 27876802, 2016). "Indeed, the Powrie group demonstrated that while suppression of colitis by wild type Treg cells was CTLA-4 dependent, CTLA-4−/− Treg cells were able to use IL-10 to elicit suppression, providing a precedent for the compensation of CTLA-4 function by the IL-10 pathway." (PMID 26596798, 2015). "Like human IBD, dysregulated activation of intestinal macrophages plays a crucial role in the development of colitis in IL-10 KO mice, as demonstrated in mice lacking IL-10 receptors or signal transducers and activators of transcription 3 in a macrophage-specific manner." (PMID 26274807, 2015). "The IL-10 KO mouse model may also be used to study probiotics, but the spontaneous colitis that progressively will occur is not homogenous, difficult to control in time and highly dependent on animal facility conditions." (PMID 25741323, 2015). "Analysis of the IL-10 deficiency model of colitis also identified a contribution of the C57BL/6J haplotype on chromosome 8 (Cdcs4, peak marker D8Mit191 at 21 cM) which main effect was limited to typhlitis and not colitis." (PMID 24487921, 2014). "Confirming the literature the Rag KO recipients of IL-10 KO CD8+ T cells did not induce colitis." (PMID 24502291, 2014). "Complete IL-10 null animals given a high-dose infection do not expel their infection and eventually develop pronounced colitis suggesting that IL-10 plays a role during both the generation of the protective type 2 response in addition to controlling IFN-γ-mediated intestinal inflammation." (PMID 24942690, 2014). "No statistically significant increase in IL-10 was observed in the colon from either KO or Wt mice following DSS challenge, nor was there any difference between unchallenged Wt and KO mice, suggesting that IL-10 may not be involved in DSS-induced colitis." (PMID 24992040, 2014). "The disease did not develop in irradiated WT mice with IL10KO or IL10/Nox1dKO bone marrow showing that the colitis could be mainly inherent to epithelial cells rather than hematopoietic lineages in IL10/Nox1dKO mice." (PMID 25014110, 2014). "This DSS colitis switches from a Th1-Th17-mediated acute inflammation with increased levels of TNF-α, IL-6 and IL-17, to a predominant Th2-mediated inflammatory response that shows a decrease in TNF-α, IL-6 and IL-17 while increasing levels of anti-inflammatory cytokines IL-4 and IL-10." (PMID 25106058, 2014). "However, levels were below the detection level in both SIGNR3−/− and wild-type mice upon colitis induction (data not shown) thus rendering a role of IL-10 unlikely." (PMID 23882266, 2013). "Interestingly, gut commensals have also been shown to activate IRAK-M expression and in the absence of both IRAK-M and IL-10, mice were more prone to developing colitis." (PMID 23776703, 2013). "TRAF2−/− mice succumb to severe colitis that result from apoptosis of colonic epithelial cells and accumulation of IL-10-secreting neutrophils, which can be ameliorated by deletion of TNFR1 or combined treatment with neutralizing antibodies against TNFα and IL-10." (PMID 23758787, 2013). "IL-10 was not significantly regulated in our TNBS-model which might suggest that IL-10 does not participate in the healing of TNBS colitis." (PMID 23382912, 2013). "For example, cystatin, the secreted product of the rat filarial nematode Acanthocheilonema viteae, was shown to protect mice from allergic airway inflammation and dextran sulfate sodium-induced colitis, and this was likely due to enhanced IL-10 production by macrophages but not Treg cells." (PMID 22558152, 2012). "This led us to hypothesize that T/I mice might be susceptible to developing colitis spontaneously, in the absence of the specific triggering required to induce colitis in Il10−/− mice." (PMID 22848611, 2012).